TP73 (tumor protein p73)
Diseases named in the same sentence as TP73 in open-access papers (continued):
Sharing a sentence is not in itself a finding about the gene and the disease.
frontotemporal dementia (1 paper, 2023). Frontotemporal dementia (FTD) comprises a group of neurodegenerative disorders, characterized by progressive changes in behavior, executive dysfunction and language impairment, as a result of degeneration of the medial prefrontal and frontoinsular cortices. "We demonstrate that TP73 variations also have contributed to ALS in the Asian population and broaden the genotypic and phenotypic spectrum of TP73 variants in the ALS-frontotemporal dementia (FTD) spectrum." (PMID 36845660, 2023). "Among the six carriers of TP73 mutations, there were both pure ALS patients and ALS patient with concomitant frontotemporal dementia." (PMID 36845660, 2023). "Following that, Pereira and colleagues linked rare mutations in TP73 with frontotemporal dementia (FTD), particularly primary progressive aphasia, which further corroborated the contribution of TP73 variations in the ALS-FTD spectrum." (PMID 36845660, 2023).
giant cell glioblastoma (1 paper, 2022).
hearing loss (1 paper, 2012). "The scientific relevance of methylation to hearing loss needs further study, as, at present, methylation of TP73 is the only mechanism implied in hearing loss pathogenesis." (PMID 22567403, 2012). "The methylation of TP73, the negative expression of cyclin D1, the positive expression of B7-H1, increased expression of platelet-derived growth factor A, underexpression of PEX5L, RAD54B, and PSMAL, and overexpression of CEA are factors associated with hearing loss and VS." (PMID 22567403, 2012).
Lissencephaly (1 paper, 2025). A spectrum of malformations of cortical development caused by insufficient neuronal migration that subsumes the terms agyria, pachygyria and subcortical band heterotopia. "Some observations support this hypothesis, apart from the fact that human deficiencies of REELIN or TP73 lead to lissencephaly and mental retardation." (PMID 40498232, 2025). "Similarly, mutations resulting in a total loss of function of TP73 in homozygous human patients also lead to lissencephaly with severe mental incapacitation." (PMID 40498232, 2025).
malignant mesothelioma (1 paper, 2020). A malignant neoplasm of the pleura or peritoneum, arising from mesothelial cells. "Using whole exome sequencing of five WDPMs of the peritoneum, we have identified distinct mutations in EHD1, ATM, FBXO10, SH2D2A, CDH5, MAGED1, and TP73 shared by WDPM cases but not reported in malignant mesotheliomas." (PMID 32545767, 2020). "Mutations in FBXO10, SH2D2A, and TP73 has not been reported in any malignant mesotheliomas." (PMID 32545767, 2020).
MALT lymphoma (1 paper, 2021). An indolent, extranodal type of non-Hodgkin lymphoma composed of small B-lymphocytes (centrocyte-like cells). "Hypermethylation of DAP-k (72.2%), GSTP1 (50%), MGMT (27.2%) and TP73 (9%) have been found in MALT lymphomas." (PMID 35008340, 2021). "CpG island hypermethylation of TP15 and TP73 genes was detected more frequently in gastric MALT lymphomas than in gastric or nodal DLBCL." (PMID 35008340, 2021).
medulloblastoma (1 paper, 2007). A malignant, invasive embryonal neoplasm arising from the cerebellum. "Furthermore, by overexpressing or knocking-down TAp73 or ΔNp73 expression, we have implicated TP73 isoforms in chemoresponsiveness of medulloblastoma." (PMID 17626635, 2007). "We have determined that primary medulloblastoma specimens and cell lines overexpress full-length TAp73 and the amino-terminal truncated variants of TP73 (ΔNp73, ΔN'p73, ΔEx2p73, and ΔEx2/3p73) at levels in excess of those found in fetal brain and normal adult cerebellum." (PMID 17626635, 2007). "The frequency and degree of TP73 overexpression in primary medulloblastoma strongly suggests the acquisition of selective advantage(s)." (PMID 17626635, 2007). "Our results support a role for TP73 in the growth of medulloblastoma and its response to genotoxic therapies." (PMID 17626635, 2007). "In order to examine the involvement of TP73 in medulloblastoma growth, we surveyed expression levels of TAp73 and total ΔNp73 variants (ΔNp73, ΔN'p73, ΔEx2p73, and ΔEx2/3p73) using qRT-RTPCR." (PMID 17626635, 2007). "Here we report TP73 overexpression in a series of primary human medulloblastoma and in established medulloblastoma cell lines, relative to normal brain tissue." (PMID 17626635, 2007). "In this study, we assessed expression of TP73 RNA species in patient tumor specimens and in medulloblastoma cell lines, and manipulated expression of full-length TAp73 and amino-terminal truncated ΔNp73 to assess their effects on growth." (PMID 17626635, 2007). "Our analysis of 34 medulloblastoma patient specimens and the medulloblastoma cell lines Daoy and D283 demonstrates significant expression of full-length, TAp73, and amino-terminal-truncated, ΔNp73, TP73 RNA transcripts and protein." (PMID 17626635, 2007). "Aberrant TP73 expression in the cerebellum may divert developing neurons from normal differentiation, leading to uncontrolled proliferation and medulloblastoma formation." (PMID 17626635, 2007). "Patient medulloblastoma samples and cell lines expressed full-length and 5'-terminal variant TP73 RNA species in 100-fold excess compared to non-neoplastic brain controls." (PMID 17626635, 2007). "Importantly, primary medulloblastoma samples expressed about 10-fold more TP73 RNA than normal adult cerebellum." (PMID 17626635, 2007). "Our results also suggest that therapeutic strategies that increase TP73 expression may be useful to augment responsiveness of medulloblastomas to chemotherapy." (PMID 17626635, 2007). "Therefore, we used medulloblastoma cell lines to assay responses to genotoxic stress in the form of chemotherapeutic agents used to treat medulloblastoma clinically (cisplatin (CDDP), etoposide (VP-16)) and another agent, doxorubicin, previously studied for TP73 induction." (PMID 17626635, 2007).
metastatic melanoma (1 paper, 2021). A melanoma that has spread from its primary site to another anatomic site. "We were able to determine the gene expression of three groups of cancer-relevant TP73 isoforms, TAp73, ∆Np73, and the ΔEx2/3p73 isoform, the latter of which was found to be upregulated in metastatic melanoma and correlated with multidrug-resistance genes." (PMID 34680379, 2021). "We were able to determine the gene expression of three cancer-relevant TP73 isoforms, TAp73, ∆Np73, and ΔEx2/3p73, the latter of which was found to be upregulated in metastatic melanoma." (PMID 34680379, 2021).
oligodendroglial tumor (1 paper, 2016). Oligodendrogliomas are cerebral tumors that are differentiated from other gliomas on the basis of their unique genetic characteristics and better response to chemotherapy. "Regarding the gene alterations among specific types of tumors, high incidence of loss of chromosome 1p and 19q and methylation of several genes, such as MGMT, estrogen receptor gene, RB1, TP73, TP14, TP15, and TP16, have been found to be characteristics of oligodendroglial tumors." (PMID 27367901, 2016).
oligodendroglioma (1 paper, 2021). A well-differentiated (WHO grade II), diffusely infiltrating neuroglial tumor, typically located in the cerebral hemispheres. "Because of the special genomic location of TP73 gene and the 1p/19q codeletion characteristic of oligodendroglioma, we further analyzed the impact of the IDH mutation and 1p/19q codeletion status on TP73 expression." (PMID 34121368, 2021).
oral cancer (1 paper, 2022). "We found that a combination of six genes (TP73, CASP8, RARB, KLLN, GSTP1, and CHFR) could distinguish oral cancer from clinically diagnosed OPMDs with high diagnostic performance (area under the curve [AUC], 0.885; sensitivity, 77.8%; and specificity, 87.1%)." (PMID 35681626, 2022). "Evaluation of the combination of six genes with aberrant methylation (RARB, KLLN, CHFR, TP73, GSTP1, and CASP8) was particularly useful for identifying early-stage oral cancer in clinically diagnosed patients with OPMDs with high diagnostic performance." (PMID 35681626, 2022).
osteosarcoma (1 paper, 2022). A usually aggressive malignant bone-forming mesenchymal neoplasm, predominantly affecting adolescents and young adults. "SETD7 increases E2F-1 stability, but inhibits E2F-1-dependent transcription of TP73 in osteosarcoma cells." (PMID 35326563, 2022). "SETD7 methylates E2F-1 at K185 stabilising it to enhance the transcription of pro-apoptotic target genes, BIM1 and TP73, suggesting that SETD7 activity inhibits cell growth and enhances the E2F-1 pro-apoptotic effect in osteosarcoma cells." (PMID 35326563, 2022).
peritoneal mesothelioma (1 paper, 2020). A benign or malignant mesothelial neoplasm that arises from the peritoneum. "Notably, we found WDPM specific mutations in EHD1, FBXO10, CHD5, MAGED1, ATM, and TP73 genes that were absent in peritoneal mesothelioma." (PMID 32545767, 2020).
prostate tumor (1 paper, 2013). "Evidence was provided to support a tendency towards reduced expression in prostate tumor tissue at DLK1, PLAGL1, SLC22A18, with less conclusive expression data for WT1 and TP73." (PMID 23890537, 2013).
renal cell carcinoma (1 paper, 2019). "For example, TP73 displayed loss of imprinting in 8 of 12 renal cell carcinomas, and two of these samples also displayed allelic switching." (PMID 31093489, 2019).
sarcoma (1 paper, 2019). A usually aggressive malignant neoplasm of the soft tissue or bone. "A cBioPortal19 query of the TCGA sarcomas displaying the TP73-/SERPINE1+ expression pattern of PS#2 reveals high probability of loss of some portion of chromosome 18q." (PMID 31562358, 2019).
sarcopenia (1 paper, 2023). Progressive decline in muscle mass due to aging which results in decreased functional capacity of muscles. "Among the four DETFs, only PAX5 exhibited significantly decreased expression, while TP73, BCL11A and TFAP2C were increased in sarcopenia." (PMID 37525094, 2023).
skin cancer (1 paper, 2022). "HNSC along with several skin cancers showed moderate to strong TP73 nuclear positivity." (PMID 35756491, 2022).
thyroid tumor (1 paper, 2025). A benign or malignant neoplasm affecting the thyroid gland. "We found new characteristics of thyroid tumors, such as methylation of TP73, WIF1, and PDLIM4 TSGs, which can contribute to thyroid neoplasia." (PMID 41150811, 2025).
tumor (121 papers, 2004 to 2025). "At the transcriptomic level, TP73 mRNA expression was high in tumour tissue compared to normal tissue and linked with shorter survival outcomes." (PMID 41153767, 2025). "TP73 transcripts were significantly higher in tumours compared to normal tissue (p < 0.0001) and linked with shorter PFS (p = 0.047)." (PMID 40244040, 2025). "TP73 encodes more than 20 isoforms through alternative splicing and promoter usage, each contributing uniquely to both tumor suppressive and oncogenic functions." (PMID 40227619, 2025). "Significantly higher levels of TP73 transcripts were also observed in tumour compared to normal tissue and linked with shorter PFS." (PMID 40244040, 2025). "Exome sequencing identified unique variants in AA patient samples within key genes, including TP73 (tumor suppression), XYLB (metabolism), ALDH4A1 (oxidative stress), PTPRB (cellular signaling), and HLA-DRB5 (immune response)." (PMID 40104216, 2025). "For the gene results, the top five genes (ranked from 17-20 and 25) were also associated with tumor formation and prognosis, including TP73 and MYC." (PMID 33912555, 2021). "We further analyzed the association between rs747828 in TP73 and colorectal cancer prognosis stratified by age, sex, smoking status, drinking status, tumor site, tumor differentiation, Dukes stage, number of metastases, and treatment in the dominant model." (PMID 31090204, 2019). "Mutations in TP73 gene in cancer are very rare and TP73-deficient mice lack a spontaneous tumor phenotype." (PMID 29733853, 2018). "TP63 and TP73 are overexpressed in human cancers, and their loss affects tumor progression and metastasis." (PMID 28258440, 2017). "The role of the Tp73 gene in oncogenic process has been underlined by several reports dealing with different tumour types." (PMID 17047653, 2006). "A higher expression of p73 was associated with poor PFS compared to tumours with low TP73." (PMID 40244040, 2025). "Furthermore, the anti-tumor role of TP73 gene in HNSC was linked to mainly five pathways including DNA replication, ribosome, apoptosis, mismatch repair, and folate biosynthesis." (PMID 35756491, 2022). "Accumulating studies have shown that the TP73 gene is closely implicated in tumor biology." (PMID 35756491, 2022). "TP73 can transform multiple variants with oncogenic and tumor-suppressive functions." (PMID 36091765, 2022). "The TP73 gene encodes two different proteins, TAp73 (i.e. V1) and ΔNp73 (i.e. V2), and maps to the small arm of chromosome 1 (1p36), a region that is often deleted in several tumors and may harbor multiple tumor suppressor genes." (PMID 31852961, 2019).
tumor (continued). "The TP63 and TP73 gene structures are complex, involving multiple promoters and splicing variations, which can produce both tumor suppressive and dominant-negative isoforms." (PMID 40227619, 2025). "It regulates the transcriptional activity of p73 (tumor protein p73), a tumor suppressor, by deacetylating its C-terminal lysine residues, leading to p73 inactivation." (PMID 40710366, 2025). "A number of imprinted tumor suppressor genes such as RB1, TP73, and CDKN1C showed copy number loss or the loss of expression in many tumor cell lines." (PMID 40414875, 2025). "Next, we investigated the differential gene expression between tumours with low and high TP73 mRNA expression (TCGA-OV cohort n = 379)." (PMID 40244040, 2025). "TP73 has been shown to have significantly higher expression in HPV+ tumour cells than HPV− tumour cells." (PMID 41462954, 2025). "Certain signaling mediators, such as mTORC1, TP73, and Beclin‐1, are crucial for the proper tumor suppressive activity of DEPDC2." (PMID 39971705, 2025). "Together, our results postulate TP73 as an interesting therapeutic target, particularly in advanced tumor stages." (PMID 39090849, 2025). "This tumor‐promoting role of TP73 would fit with the recently proposed model of metastasis evolution in which the co‐option of developmental programs increases metastatic potential." (PMID 39090849, 2025). "Of these, splicing out of exon 2 (ΔEx2TP73) was reported using PCR amplification followed by hybridization or by using radiolabelled PCR, and represents a minor form of TP73 transcripts seen only in tumour cells." (PMID 39404067, 2024). "In this regard, we examined the splicing pattern of TP73 in normal and tumor tissues by using the TCGA SpliceSeq database." (PMID 37650871, 2023). "The expression of TP73 was significantly higher in the subgroup tumor patients with response to treatment (PR & CR) compared with the subgroup tumor patients without response to treatment (PD & SD, P = 0.011)." (PMID 35756491, 2022). "Similar to TP63, TP73 showed systematically increased expression in the tumor tissues of the SC types." (PMID 35227282, 2022). "In step 6, we explored the role TP73 played in tumor immunity by investigating TIICs, the tumor immune microenvironment and immunomodulatory genes." (PMID 35756491, 2022). "Previous immunohistochemistry results also identified an elevated expression of TP73 protein in HNSC tumor samples." (PMID 35756491, 2022). "Our current research demonstrated that TP73 gene was overexpressed in HNSC tumor tissue as compared to control samples." (PMID 35756491, 2022). "The relationship between TP73 and immunological aspects, including immune cells, immune inhibitor genes, immune stimulator genes, and tumor immune microenvironment, were investigated." (PMID 35756491, 2022). "TP73 modulates immune cells in the tumor microenvironment of HNSC patients, thereby bearing significance for HNSC immunotherapy." (PMID 35756491, 2022). "TP73 was found to be positively correlated with the majority of tumor infiltrating immune cells and immunoinhibitory genes in HNSC." (PMID 35756491, 2022). "The elevated expression of TP73 was observed in the subgroup tumor patients with younger age (≤60) compared with older age (>60, P = 0.035)." (PMID 35756491, 2022). "Recent studies have shown that ferredoxin reductase regulates the expression of TP73 by binding to iron-binding proteins, thereby regulating aging and tumor inhibition." (PMID 34257653, 2021).